FANCM (FA complementation group M)
Description:
DNA-dependent ATPase component of the Fanconi anemia (FA) core complex. Required for the normal activation of the FA pathway, leading to monoubiquitination of the FANCI-FANCD2 complex in response to DNA damage, cellular resistance to DNA cross-linking drugs, and prevention of chromosomal breakage. In complex with CENPS and CENPX, binds double-stranded DNA (dsDNA), fork-structured DNA (fsDNA) and Holliday junction substrates. Its ATP-dependent DNA branch migration activity can process branched DNA structures such as a movable replication fork. This activity is strongly stimulated in the presence of CENPS and CENPX. In complex with FAAP24, efficiently binds to single-strand DNA (ssDNA), splayed-arm DNA, and 3'-flap substrates. In vitro, on its own, strongly binds ssDNA oligomers and weakly fsDNA, but does not bind to dsDNA.
Synonyms: FAAP250; KIAA1596; POF15; SPGF28
Tractability: PROTAC: ubiquitination databases record sites on it.
Gene: Protein-coding gene on chromosome 14 (45,135,909 to 45,200,890, forward strand). Ensembl gene ENSG00000187790.
Subcellular location: Nucleus
Subcellular location (Human Protein Atlas): Nucleoplasm
Pathways (Reactome):
DNA Repair: Fanconi Anemia Pathway
Immune System: PKR-mediated signaling
Gene Ontology:
Molecular function: ATP hydrolysis activity; chromatin binding; protein binding; 3'-5' DNA helicase activity; four-way junction DNA binding; four-way junction helicase activity; ATP binding; DNA binding; nucleic acid binding; RNA helicase activity
Biological process: interstrand cross-link repair; positive regulation of protein monoubiquitination; replication fork processing; resolution of meiotic recombination intermediates; double-strand break repair via synthesis-dependent strand annealing; DNA repair; homologous recombination
Cellular component: chromatin; FANCM-MHF complex; Fanconi anaemia nuclear complex; nucleoplasm; nucleus; cytosol
Genetic constraint (gnomAD): Loss-of-function variants: 68 observed, 110.34 expected, observed/expected ratio (o/e) 0.62, 90% interval 0.51 to 0.75. The upper end of that interval is the gene's LOEUF score, 0.75, which puts it in group 3 of 6, group 1 being the genes least tolerant of losing a copy. Missense variants: 1,635 observed, 1,714.4 expected, observed/expected ratio (o/e) 0.95, 90% interval 0.92 to 0.99. Synonymous variants: 601 observed, 625.63 expected, observed/expected ratio (o/e) 0.96, 90% interval 0.9 to 1.03.
Gene-disease validity (ClinGen):
ClinGen rates the evidence that FANCM causes each of these diseases.
FANCM Fanconi-like genomic instability disorder (autosomal recessive): Definitive. FANCM Fanconi-like genomic instability disorder is autosomal recessive condition associated with an increased risk of cancer, infertility, and hypersensitivity to cytotoxic agents.
hereditary breast carcinoma (autosomal dominant): Limited. Breast carcinoma that has developed in relatives of patients with history of breast carcinoma.
Fanconi anemia (autosomal recessive): Refuted. Fanconi anemia (FA) is a hereditary DNA repair disorder characterized by progressive pancytopenia with bone marrow failure, variable congenital malformations and predisposition to develop hematological or solid tumors.
Cancer hallmarks: genome instability and mutations (suppresses); proliferative signalling (promotes)
Homologues: Orthologues: chimpanzee FANCM (99% identical), macaque FANCM (95% identical), dog FANCM (79% identical), rabbit FANCM (77% identical), pig FANCM (76% identical), guinea pig FANCM (72% identical), mouse Fancm (65% identical), rat Fancm (64% identical), tropical clawed frog fancm (44% identical), Drosophila melanogaster Fancm (19% identical).
Diseases named in the same sentence as FANCM in open-access papers:
FANCM is named in the same sentence as 101 diseases in open-access papers, as found by Europe PMC text mining. Sharing a sentence is not in itself a finding about the gene and the disease. The quoted sentences say what the papers report.
Fanconi anemia (80 papers, 2011 to 2026). "FANCM encodes a member of the Fanconi Anemia complementation group, and is an essential gene involved in DNA repair." (PMID 39990381, 2025). "This study reveals how FANCM evolved from an ancient repair motor into a specialized sensor coupling DNA-damage recognition to Fanconi Anemia pathway activation, with implications for cancer predisposition and therapeutic targeting." (PMID 40447800, 2025). "Biallelic FANCM variants are linked to a Fanconi anemia‐like cancer predisposition syndrome, which includes early onset breast cancer, chemotherapy toxicity, and chromosome fragility." (PMID 40832744, 2025). "Mutations in the FANCM gene are associated with Fanconi anemia (FA), a rare genetic disease characterized by defects in development, bone marrow failure and cancer predisposition." (PMID 38847937, 2024). "Fanconi Anemia (FA) Complementation Group M (FANCM) has recently been reported as one such susceptibility gene." (PMID 36835452, 2023). "Other susceptibility genes have been identified; Fanconi Anemia Complementation Group M (FANCM) being one of these." (PMID 36835452, 2023). "We also found specific upregulation of genes of the Fanconi anemia pathway, in particular FANCM, FANCD2 and FANCI, which encode known interaction partners of BLM." (PMID 35099000, 2022). "Within the 12 families, three variants were found in FANCC and FA complementation group M (FANCM) that were associated with Fanconi anemia and spermatogenic failure, respectively." (PMID 35877578, 2022). "Ewing sarcoma cell lines such as SKPNDW and ES7 harbor pathogenic somatic variants in FANCM (Fanconi anemia, complementation group M)." (PMID 36187937, 2022). "In the context of interacting genes coding for disease-causing putative proteins, we found that FANCM and its interacting partner participate in the DNA repair pathway and Fanconi anemia pathways (also involved in DNA repair)." (PMID 34021221, 2021). "FANCM is a member of Fanconi Anemia (FA) core complex, whose defects are associated with cell hypersensitivity to DNA interstrand crosslink (ICL)-inducing agents." (PMID 34976027, 2021). "The human ortholog of Hef (hHef) was identified as FANCM, and it is known that mutations in the FANCM gene are the cause of Fanconi anemia, a hereditary genetic disease." (PMID 29209094, 2017). "Defects in HR and increases in chiasma frequency have also been reported in plants with mutations in FANCM (Fanconi anemia complementation group M), which encodes for a DNA translocase required for the repair of DNA inter-strand CLs." (PMID 24904598, 2014). "Additionally, mutations in the Fanconi Anemia genes, FANCM (1, 1.8%) and FANCA (1, 1.8%), were also found." (PMID 35205662, 2022). "Here, we show that SMC5 dysfunction in avian DT40 B cells causes mitotic delay and hypersensitivity toward DNA intra‐ and inter‐strand crosslinkers (ICLs), with smc5 mutants being epistatic to FANCC and FANCM mutations affecting the Fanconi anemia (FA) pathway." (PMID 31867888, 2020). "Since the generation of HAP1 FANCG and FANCM knockout cell lines has also been reported recently, loss of expression of Fanconi anemia-associated genes might rather slow down cellular proliferation than directly inducing cell death." (PMID 33228647, 2020). "FANCM has DNA-dependent ATPase activity, promotes the dissociation of DNA triplexes, and with other Fanconi anemia-associated proteins, may repair DNA at stalled replication forks." (PMID 21619704, 2011). "FANCM is crucial in genome maintenance, functioning in the Fanconi anemia (FA) pathway, alternative lengthening of telomeres (ALT), and replication fork protection." (PMID 40447800, 2025).
Fanconi anemia (continued). "FANCM is a member of the Fanconi Anemia (FA) complex and is the most conserved gene within the FA pathway." (PMID 40841357, 2025). "This indicates that the DNA-remodelling motor function of FANCM is required in SMARCAL1-deficient cells, but its recruitment of the Fanconi anaemia and BLM–TOP3A–RMI complexes is dispensable." (PMID 40205037, 2025). "The genes FANCM, FANCA and XRCC2 are also directly involved in the Fanconi anaemia pathway, as biallelic variants in these genes can cause Fanconi anaemia." (PMID 39257928, 2024). "Eukaryotes contain a homolog to the archaeal Hef protein, and the human protein is called FANCM, because it is one protein of a protein complex that is related to Fanconi anemia." (PMID 39062640, 2024). "ICL traversal also depends on ATR and the Fanconi anemia pathway and involves, among other proteins, FANCM, FANCD2 and PRIMPOL." (PMID 39766854, 2024). "Li X., Yu M., Bolaños-Villegas P., Zhang J., Ni D., Ma H., Wang Y.Fanconi anemia ortholog FANCM regulates meiotic crossoverdistribution in plants." (PMID 37063511, 2023). "Fanconi anemia genes constitute a critical DNA damage response pathway, and it is suggested that FANCM prevents the lengthening of telomeres in cancer cells." (PMID 36814285, 2023). "These genes include DDIT3 (DNA damage-inducible transcript 3), FANCM (Fanconi anemia, complementation group M), Merlin tumor suppressor, NME1 (NME/NM23 nucleoside diphosphate kinase 1), SMAD4." (PMID 37239070, 2023). "In the context of the FA/BRCA pathway, ATR will be involved in the initial recognition of ICLs, will phosphorylate FANCM, as well as Fanconi Anemia Complementation Group I (FANCI) for promoting the activation of the FA pathway." (PMID 36091172, 2022). "TraesCS3B02G048300 (3BS8-0.78-0.87) is annotated as a member of the Fanconi anemia group M protein, related to FANCM, that acts as an anti-crossover protein." (PMID 36079661, 2022). "Bra034416, BniB042826 and Bol031970 are orthologous to FANCM (Fanconi anemia complementation group M), a highly conserved helicase, which functions as a major factor limiting meiotic CO formation." (PMID 35736707, 2022). "FANCM [Fanconi Anemia (FA) complementation group M, OMIM: 609644], which is located in chromosome 14q21.2, is associated with Fanconi Anemia (FA) and Bloom Syndrome (BSyn) diseases." (PMID 34067580, 2021). "FANCM is involved in eukaryotic DNA-damage recognition and activates the Fanconi anemia (FA) pathway through complex formation." (PMID 33439149, 2021). "FANCM is part of the Fanconi anemia (FA) core complex, which contributes to the functionality of DNA repair machinery." (PMID 33669748, 2021). "FANCM, a component of the Fanconi anemia complex, was considered a tumor suppressor involved in DDR, until very recent studies showed a novel role in telomere maintenance, specifically in cancer cells with alternative lengthening of telomeres (ALT)." (PMID 32680567, 2020). "Variant rs10138997 (FANCM) and variants rs3810812 and rs28516461 (SLX4) are Fanconi anemia (FA) disease associated (NCBI ClinVar)." (PMID 32708070, 2020). "Human FANConi anemia, complementation group M (FANCM) is a highly conserved protein with ATPase and DNA translocase activity, belonging to the Fanconi anemia (FA) core complex." (PMID 31552268, 2019). "The first anti-CO protein identified through these screens was FANCM (Fanconi Anemia Complementation Group M)." (PMID 29628933, 2018). "FANCM has long been recognized as a core component of the Fanconi Anemia pathway, a network of at least 22 proteins identified in human that preserve genome stability by promoting the processing of interstrand crosslinks." (PMID 29628933, 2018). "Six patients had mutations in FANCA, FANCI, FANCL, FANCM and SLX4 genes, which are involved in Fanconi anemia (FA)." (PMID 28423363, 2017).
Fanconi anemia (continued). "We also identified several SCD-containing proteins that play key roles in DNA repair and that are mutated in patients suffering from Werner Syndrome (WRN) and Fanconi Anemia (FANCM)." (PMID 26743489, 2016). "Here, we demonstrate that FANCM, a component in the Fanconi Anemia pathway, is a novel target of miR146a." (PMID 27351285, 2016). "FANCM and MHF2 are both Fanconi Anemia (FA) associated proteins, prompting us to test the other FA genes conserved in Arabidopsis for a role in CO control at meiosis." (PMID 25038251, 2014). "STRA13 (also known as CENP-X or MHF2) is the DNA-binding component of the Fanconi Anemia (FA) core protein complex, through its association with MHF1 and FANCM proteins." (PMID 23518061, 2013). "There were 4 SNPs in the DNA repair gene FANCM (Fanconi anemia, complementation group M) and 2 SNPs in the growth and hormone gene GH1 that were significantly associated with OS after correction for multiple tests." (PMID 21619704, 2011). "HFE rs1800562 causing hereditary hemochromatosis presented the highest frequency (7.54%), followed by BTD rs13078881 for biotinidase deficiency (7.08%), FLG rs61816761 for ichthyosis vulgaris and atopic dermatitis (3.38%), and FANCM rs147021911 for Fanconi anemia (3.08%)." (PMID 40763936, 2026). "Wild-type FANCM and variants lacking the Fanconi anaemia core complex-binding MM1 (Δ943–1004) or BLM–TOP3A–RMI complex-binding MM2 domain (Δ1,219–1,251) rescued the synthetic lethality." (PMID 40205037, 2025). "ICLs are recognized during S phase, mainly by the UHRF1 protein which, together with an anchor complex composed of Fanconi Anemia Complementation Group M (FANCM) and FAAP24, ensure the recruitment of the FA core complex and the FANCD2-I heterodimer to the appropriate location in the chromatin." (PMID 36091172, 2022). "This interplay of RAD52 and FANCM was important in the repair and stability of common fragile sites, and relied on the translocase activity of FANCM rather than its association with the rest of the Fanconi anemia (FA) core complex." (PMID 31340507, 2019). "The recruitment of FANCM, a conserved DNA translocase and key component of several DNA repair protein complexes, to replication forks stalled by DNA interstrand crosslinks (ICLs) is a step upstream of the Fanconi anemia (FA) repair and replication traverse pathways of ICLs." (PMID 28058110, 2016). "FANCM is a DNA translocase that can form independent functional interactions with the BLM-TOP3A-RMI (BTR) complex and the Fanconi anemia (FA) core complex." (PMID 31138797, 2019). "Due to involvement of FANCM, FANCJ and FANCP homologues (Mph1, Chl1 and Slx4), this pathway has been described as a Fanconi anemia-like pathway." (PMID 27636878, 2016). "FANCM protein is a component of the Fanconi anemia (FA) core complex, but FANCM is not a canonical FA gene." (PMID 40832744, 2025). "In our study, moderately increased BC risk was defined for mutations in the Fanconi anemia genes FANCC (OR = 2.4) and FANCI (OR = 4.3), but not for FANCM (OR = 0.6), although the difference was not significant." (PMID 39684352, 2024). "Interestingly, more than half of the possible pathogenic variants identified in patients with mesothelioma were located within genes of the Fanconi anemia pathway (FANCA, FANCC, FANCD2, and FANCM)." (PMID 31263571, 2019). "Additionally, Su-Dhl-4 cells treated with entinostat or tazemetostat also showed downregulation of RAD51, RAD54L, BRCA2, and three Fanconi anemia genes (FANCA, FANCB, and FANCM)." (PMID 31829282, 2019).
Fanconi anemia (continued). "Additionally, we found 7 monoallelic pathogenic variants (2%, 7/327) in 6 genes (besides BRCA1/2) of the interstrand crosslink DNA repair Fanconi anemia pathway (FANCB, FANCC, FANCF, FANCI, FANCL, FANCM) and 1 in RAD51C, a Fanconi-like phenotype gene." (PMID 30262796, 2018). "In our efforts to understand the molecular basis of treatment response in advanced cervical cancer, besides the BRCA pathway, we also found the fanconi anemia (FA) complementation group, FANCD2, FANCL, FANCM, FANCJ/BRIP1/BACH and FANCI, to be involved in intrinsic resistance to chemo-radiotherapy." (PMID 24708616, 2014). "Intriguingly, this hypothetical FANCM/NEIL-dependent pathway does not require involvement of other DNA repair systems such as NER, HR, structure-specific endonucleases or the Fanconi anemia system and thus does not generate highly genotoxic DNA repair intermediates." (PMID 29234069, 2017).